NF2 (NF2, moesin-ezrin-radixin like (MERLIN) tumor suppressor)
Diseases named in the same sentence as NF2 in open-access papers (continued):
Sharing a sentence is not in itself a finding about the gene and the disease.
tumor (continued). "The Hippo core components and upstream regulators such as NF2 and MST are predominantly involved in tumor suppressor function, whereas TAZ, YAP, and TEADs are involved in oncogenic events." (PMID 23986776, 2013). "The overall similarity in tumor burden among these conditions is striking given the diverse functions of the NF1, NF2, and SMARCB1 tumor-suppressor genes." (PMID 22558206, 2012). "Therefore, identification of gross deletions of NF2 gene in a set of patients from Croatia (the first time on a southeastern European population) can contribute to our knowledge of the total frequency of NF2 alterations and thus improve our understanding of this tumor’s etiology." (PMID 22911524, 2012). "Subgroup analysis showed that age ≤ 19 years was a significant negative prognostic factor for tumor control in NF2‐VS patients (p < 0.001), whereas no such correlation was found in the S‐VS cohort (p = 0.78)." (PMID 41454441, 2026). "Specifically, among all the enriched targets, NF2, ARID1A, and TGFBR2 emerged as the top 3 enriched targets that were identified in more than half of the replicates, highlighting their substantial effect on tumor development." (PMID 41480763, 2026). "In this study, we have employed high-dimensional imaging to analyse in detail the spatial architecture of NF2 SWN-related VS, highlighting that these tumours exhibit a complex topology with tumour-rich and immune cell-rich zones across histomorphic niche Antoni A and B regions." (PMID 40140675, 2025). "Fortunately, 95% of patients with acoustic neuroma do not have NF2 and present with a single-sided tumor." (PMID 41278265, 2025). "Mosaic NF2-related SWN can be difficult to identify by genetic testing without at least two tumours being available for analysis in addition to blood." (PMID 40794298, 2025). "Therefore, there is an urgent need to identify new therapeutic targets for the treatment of NF2-SWN patients, especially using agents that are effective across the different tumour-types." (PMID 41437121, 2025). "When NF2 was inhibited and YAP was overexpressed in TNBC cells, CD24 and FSP1 were inhibited, resulting in enhanced ferroptosis and TAM phagocytosis, hindering TNBC tumor growth." (PMID 39796693, 2024). "NF2 is a known tumor suppressor which, under non-cancerous conditions, acts to regulate cell proliferation and growth." (PMID 39796693, 2024). "Loss of chromosome 22 was detected in two small meningothelial nests, whereas the somatic mutations in NF2 and CREBBP found in the mass-forming tumor were not present." (PMID 39066986, 2024). "Significant tumor responses were observed in seven of nine models, with deep tumor regressions in three NF2-altered models and durable tumor stasis in four other models without reported Hippo alterations." (PMID 38565920, 2024). "As expected, knockout (KO) of Nf1 or Tsc1 or Tgfbr2, but not Nf2, increased the number of spontaneous lung metastatic nodules and increased the primary tumor size." (PMID 38997291, 2024). "Controls were well matched for age at NF2 diagnosis and treatment (Males = 133%–50%) and had no M/MP in the CNS post-index tumor treatment (P = .0016)." (PMID 37051330, 2023). "The high abundance of tumour-associated macrophages and presence of T-cells noted in this study promote these immune cells as potential immunotherapeutic avenues to modify the tumour immune microenvironment in order to reduce tumour growth and SNHL in patients with either NF2-SWN or sporadic VS." (PMID 37680691, 2023). "Despite the well-known NF2 role as a tumor suppressor, no new chemotherapeutic approaches have yet been developed, probably due to its broad involvement in different signaling pathways and interaction with multiple protein partners." (PMID 36937440, 2023). "Furthermore, the inflammatory profiles of these macrophages appear consistent between NF2-SWN and sporadic tumours when validated by qPCR in an additional cohort of VS samples." (PMID 37680691, 2023).
tumor (continued). "He met clinical criteria for NF2 from his tumor types and underwent germline genetic testing using a saliva sample for NF1, NF2, LZTR1, and SMARCB1, which did not demonstrate any mutations." (PMID 38058737, 2023). "Overall, when comparing NF2-SWN and sporadic VS against nerve samples, the similarities in immune-related signalling pathways and gene expression imply a rich immune component to the tumour microenvironment in both NF2-SWN and sporadic VS." (PMID 37680691, 2023). "NF2, FAM3B, and MGMT are primarily involved in regulating the tumor immune microenvironment." (PMID 37264476, 2023). "Furthermore, the presence of T-cells in immune-rich niches was observed in both NF2-SWN and sporadic VS, indicating the similarities in their tumour immune microenvironments." (PMID 37680691, 2023). "In contrast, the injected control Nf2-positive hepatoblasts were scattered uniformly throughout the liver and did not form neoplasms." (PMID 37174657, 2023). "This proved not to be the case; the Cd44 gene status had no influence on the development of primary liver tumors in Nf2flox/flox;Alb-Cre mice, suggesting that deletion of Nf2 leads to tumor-promoting mechanisms independent of Cd44." (PMID 37174657, 2023). "Using high-throughput deep sequencing, 2-hit alterations in the neurofibromatosis 2 (NF2) gene were identified in every tumor and not in peripheral blood, supporting that all events were somatic." (PMID 36341135, 2022). "The most common alterations were BAP1 mutations (n = 5; of note, BAP1 was assessed only by the 14MG panel and only in the tumour specimen, no germline analysis), CDKN2A loss (n = 2) and NF2 mutation (n = 2; to note, NF2 was assessed only by the 14MG panel)." (PMID 35585228, 2022). "While no specific gene has been identified other than the NF2 gene, several other possible mechanisms of tumorigenesis or tumor growth have been revealed, especially in the recent comprehensive data provided by omics analysis." (PMID 35626200, 2022). "ATRX, CSDE1 and NF2 become the top SNA-based, CNA-based and mixed tumour suppressors, respectively." (PMID 35975235, 2022). "They state that NF2 tumor analysis had already shown potential for increasing understanding of all neoplasia, not simply neoplasia limited to NF." (PMID 35481324, 2022). "Second post-CIR time point identified cullin 7 (CUL7) and last time point acyl-coa synthetase long chain family member 4 (ACSL4) with NF2, OBSL1 and YWHAE as highly connected components, all being described or hypothesized to play roles in tumor development." (PMID 35158950, 2022). "The OPG of P24 with genetically detected pathogenic NF2 variation was diagnosed neuroradiologically because of the OPG-characteristic appearance on MRI, therefore no biopsy from the tumor was performed." (PMID 34325699, 2021). "Notably, outliers with extreme negative BFs in BAGEL2 (red) include genes with known tumor suppressor activity, including KEAP1 and Hippo pathway genes NF2 and KIRREL." (PMID 33407829, 2021). "Although NF2 inactivation is clearly a driver of mesothelial carcinogenesis, it is possible that this inactivation does not play a role in tumor initiation for MPM, but will promote the development of a more aggressive tumor." (PMID 34261524, 2021). "Although not FDA-approved, bevacizumab is used off-label for NF2 patients, with some of them experiencing tumor reduction and improved hearing." (PMID 34604034, 2021). "NF2 drug development is often hindered by a relative lack of in vitro models that replicate tumor pathophysiology with high fidelity." (PMID 33604573, 2021).
tumor (continued). "In the absence of exogenous growth factors, NF2‐mutant tumor cells rely on YAP/TAZ‐signaling to maintain growth‐promoting signaling through engaging the activities of AKT and RTKs." (PMID 33410252, 2021). "Significantly, the key signature cytokine IL-10, known to be produced by all M2 macrophage phenotypes, was nearly four-fold higher in the NF2-negative tumours." (PMID 32070062, 2020). "Our data also argue that LATS2 and NF2 may exert distinct roles in MPM, at odds with the long-held assumption that they act as tumor suppressors through the Hippo pathway." (PMID 32824422, 2020). "However, the obvious difference between NF2 and other members of ERM is that it can inhibit tumor growth." (PMID 32337368, 2020). "STX3451 and STX2895 also increased the percentage of annexin V positive IOMM-Lee cells, but this increase was not statistically significant, indicating that NF2 wild-type tumour cells are less sensitive to the 2ME2 analogs." (PMID 31730023, 2019). "The same approaches in the present study on NF2 led to the findings that, in NF2 human tumour cells, none of the pathways that were found to be affected in NF1 was affected in NF2." (PMID 31730023, 2019). "Vision in patients with NF2 is commonly compromised independent of the risks posed by tumors of the optic apparatus." (PMID 30356733, 2018). "In sum, these results suggest that both primary human VS cultures and an NF2-derived VS cell line overexpress αv integrins and NRP-1 on the cell surface, which can be harnessed for receptor-targeted, tumor-penetrating delivery of therapeutics via the CendR pathway." (PMID 29018206, 2017). "Principal component analysis, unsupervised hierarchical and consensus clustering clearly distinguished NF2 CNV-low, NF2 CNV-high and non-NF2 samples, however failed to completely separate atypical versus benign tumours." (PMID 28195122, 2017). "The transcriptional coactivator YAP is a major downstream negative effector of the Hippo pathway 6, 7 and is tightly negatively regulated by a series of upstream components such as NF2, LATS1/2, MST1/2 and SAV1, which are tumour suppressors in several types of human cancers." (PMID 28470935, 2017). "XAV939 phenocopied the effects of dnTEAD4 in inhibiting TEAD transcriptional activity and inducing a G1 growth arrest in most of the LATS or NF2 mutant tumor lines analyzed without detectable growth inhibitory effects on other cells tested." (PMID 27144834, 2016). "As the frequency of NF2 mutation is roughly equal among the different WHO grades, it has been considered a relevant genetic alteration in tumor initiation rather than in malignant progression." (PMID 25965831, 2015). "After that, the whole coding sequence of NF2 and SMARCB1 genes were sequenced in tumor T1." (PMID 25739810, 2015). "Also consistent with the CGP results is lapatinib’s (row-clade d) sensitivity to tumor cells with ERBB2_MUT (column-clade E), which, according to these results, is also accompanied by MUTs in CCND1, NF2 and SMAD4." (PMID 26132924, 2015). "Additionally, we did not observe increased tumour formation in any organ of iso1 ko or iso2 ko animals up to 26 months of age, regardless of its initial Nf2 isoform expression pattern, although heterozygous inactivation of Nf2 in mice causes the development of multiple tumours within one year." (PMID 26258444, 2015). "The LC is not statistically significantly different when other factors are compared, including the presence or absence of NF-2, patient age, prior surgical intervention vs no prior surgical intervention, tumor size and tumor volume." (PMID 24142966, 2014).
tumor (continued). "Furthermore, it has been shown that NHeRF1 binds to the breast tumor suppressor SYK and MERLIN, the product of the tumor suppressor NF2." (PMID 22973555, 2012). "In this study, we have not used any tumour smaller than 3.5 cm in diameter and we have not used any bilateral NF2 tumour samples." (PMID 23304241, 2012). "Tumor stromal pathways are also in evidence with the common genes including; TLR4, TLR7, HLA-DRA, HLA-DQA1, CXCR4, FOS and TGFB2 (immune surveillance and chemokine pathways) and NF2, ITGA7, PGF, ITGA4, PDGFD and PARVA (focal adhesion)." (PMID 23226201, 2012). "Finally, patients with neurofibromatosis 2 (NF2) have decreased expression levels of merlin, an ERM-related protein that acts as a tumor suppressor." (PMID 21437219, 2011). "And while it has been shown that EBP50 can cluster with EGFR, PDGFR, and the tumor suppressor NF2 to halt cell signaling and hence cancer progression, others have posited that EBP50's PDZ domains may actually allow for new tumor-specific interactions." (PMID 21672215, 2011). "Multiple ligation-dependent probe amplification analysis of the NF2 gene demonstrated no additional copy number aberrations in blood or tumours of this patient (data not shown)." (PMID 18087273, 2008). "As a result, the applicability of outcomes drawn from more selectively chosen NF2 cohorts—often consisting of patients with preserved hearing or indolent tumor growth—may not extend to all phenotypic subgroups." (PMID 41085808, 2025). "Importantly, beyond diagnostic value, the differing biology of Antoni A and Antoni B regions of NF2 SWN VS tumours has not been previously explored in detail until now." (PMID 40140675, 2025). "All four hits are not always detectable in every non-NF2-related tumour, but this may be due to several reasons, such as the presence of non-tumour cell DNA in the sample." (PMID 41284083, 2025). "Finally, tumor SP‐06 presented genetic alterations in genes NF2, SMARCA4, and NRAS, which may point to other tumor entities." (PMID 37798904, 2024). "NF2 may regulate PD‐L1 expression through the PI3K–AKT–mTOR pathway, anti‐PD‐L1 antibody may have a synergetic effect with the mTOR inhibitor in reducing tumor cell proliferation." (PMID 38828669, 2024). "Nevertheless, previous studies have reported that NF2 plays pivotal roles in cell contact inhibition, mitogenic signal transduction inhibition, proteolysis, epithelial adhesion, and polarity, but the biological roles of NF2 in tumor metabolism and immunity have not been systematically discussed." (PMID 38879686, 2024). "LXXVIPatients with NF2 may receive a CI, even without tumor resection or with partial resection (if it is neurologically safe), because this approach can increase the chances of cochlear nerve function preservation." (PMID 39442262, 2024). "At the time of diagnosis, no NF2-related tumor was disseminated." (PMID 39713042, 2024). "Cytotoxicity is a desired endpoint as it suggests that CUDC907 could reduce tumor burden in NF2 patients as opposed to preventing tumor progression." (PMID 35875610, 2022).
tumor (continued). "As previously discussed in the Children’s Tumor Foundation forum, Dr. M. Wootton, CEO of NF2 Therapeutics, mentioned that they have a monkey model of NF2 gene replacement, and based on this, he went on to state that the first human clinical trials for this NF2 transgene may start in 2022 or 2023." (PMID 33445724, 2021). "In the patient M17, even with a good quality of biopsy material, no NF2 genetic alteration was detected but the issue could be the area of tumor biopsy in this huge tumor." (PMID 32642718, 2020). "Growth inhibition by rapamycin, an immunosuppressant drug, was demonstrated using an in vitro cell model and a mouse model for NF2 followed by a phase II trial, where everolimus was applied to 10 NF2 patients, which failed to reach the primary endpoint of tumor volume reduction." (PMID 31291992, 2019). "Furthermore, the strength of the immunohistochemical staining was not correlated to tumor size, hearing function, or NF2." (PMID 29515781, 2018). "Furthermore, we confirmed the downregulation of ITGA7, which was reported to be epigenetically deregulated in MPM and suggested as therapeutic and prognostic marker, and the downregulation of NF2, altered in almost half of MPM tumours with an important prognostic impact." (PMID 27835874, 2017). "When comparing uRCC with NF2 loss (n=16) to those without (n=43), there was a statistically significant stronger nuclear YAP/TAZ signal, correlating with negative to very low phospho-YAP signal, in NF2 loss tumours." (PMID 27713405, 2016). "Thus far, none of the ERM proteins has been identified as a bona fide tumor suppressor except Merlin (moesin-ezrin-radixin-like protein), which was identified as the gene for neurofibromatiosis-2 (NF-2)." (PMID 18554410, 2008). "A genome-wide and high-resolution copy number analysis could contribute to identify additional genetic alterations involved in tumor development, especially for the meningothelial subtype, which does not commonly display NF2 and 22q alterations." (PMID 17222329, 2007). "However, epigenetic mechanisms may not be the primary drivers of tumour formation in NF2, warranting further investigation." (PMID 40843672, 2025). "Cancer gene panel testing of the retroperitoneal tumor sample showed a base substitution in ARID1A (splice site 2251+2T>G), duplication of exons 5–31 in NOTCH2, frameshift mutation in MSH6 (D387fs*4), and deletion of exons 5–9 in NF2, none of which were treatable target in the present case." (PMID 38739347, 2024). "Thus, our results suggest that deletion of Nf2 may specifically release tumor-promoting mechanisms that are independent of CD44; or alternatively, CD44 function is compensated by other molecules in Cd44-deficient Nf2-mutant mice." (PMID 37174657, 2023). "Additionally, to explore the gene expression of tumour microenvironment signatures, a panel of genes determined from the literature and IPA’s ‘Molecules’ function to represent Schwann cells, vasculature and immune cells were assessed in nerve, NF2-SWN VS and sporadic VS." (PMID 37680691, 2023). "Similar to sporadic VS studies, those focusing on NF2 populations also highlighted the lack of a clear size threshold for symptom severity, and the need for more complex clinical studies to tackle discordant results between tumor size and hearing in NF2 patients." (PMID 35372070, 2022).